ENSG00000309144 (novel transcript)
Gene: Long non-coding RNA gene on chromosome 8 (22,244,279 to 22,245,035, reverse strand). Ensembl gene ENSG00000309144.
Gene Ontology:
Biological process: cellular response to glucose stimulus; long-term synaptic potentiation; miRNA-mediated post-transcriptional gene silencing; negative regulation of gene expression; positive regulation of stem cell proliferation
Cellular component: RISC complex